INS (insulin)
Diseases named in the same sentence as INS in open-access papers (continued):
Sharing a sentence is not in itself a finding about the gene and the disease.
Insulin resistance (continued). "Other indicators based on serum insulin levels, such as the homeostasis model assessment for insulin resistance (HOMA-IR), the oral glucose insulin sensitivity index, and the McAuley index, are not suitable for diabetic patients undergoing insulin treatment." (PMID 40672456, 2025). "Insulin levels and insulin resistance (HOMA-R) showed significant increases with positive mean differences between Non-CO-CSIR and CO-CSIR, and CO and CO-CSIR (F = 5.1 for Insulin, F = 16.7 for HOMA-R, P < 0.05)." (PMID 41415265, 2025). "Conversely, pooled analyses evaluating the effects on insulin resistance indices (HOMA-IR, fasting insulin concentrations) reported inconclusive or non-significant results." (PMID 41441014, 2025). "Homeostasis Model Assessment for Insulin Resistance (HOMA-IR), a commonly used tool for assessing IR, is not applicable to patients undergoing insulin therapy or those with β-cell dysfunction." (PMID 40397902, 2025). "Our data also confirmed that i.p. trehalose treatment is therapeutically effective against weight gain and insulin insensitivity, but strikingly that oral-only administration failed to rescue HFD-induced obesity and insulin resistance." (PMID 40529415, 2025). "Moreover, fasting insulin levels may not be the optimal indicator for assessing insulin resistance." (PMID 40361863, 2025). "Additionally, insulin sensitivity, measured using the HOMA2 index, was significantly lower at day of life 7 (HOMA index of 3.6) compared to 36 weeks (HOMA index of 1.6), reinforcing the notion that early metabolic stress in preterm infants may lead to lasting insulin resistance." (PMID 40519768, 2025). "Insulin resistance is a state of prediabetes where glucose transporters GLUTs (mainly GLUT1, GLUT2, GLUT3, and GLUT4) do not respond to the action of the hormone insulin on insulin receptors (a defect in the signal transduction cascade initiated by insulin)." (PMID 41303162, 2025). "Twenty (66.7%) patients had resistance to insulin (HOMA-IR ≥ 2.5), while insulin resistance was absent in seven patients." (PMID 41233800, 2025). "Notably, the primary insulin-regulated step may not be the one most impacted by insulin resistance." (PMID 40806697, 2025). "However, in insulin-stimulated cells, these agents did not sufficiently suppress the uptake of glucose, and at a deuterium concentration of 50 ppm, where the maximum glucose uptake was observed, 45–70% of the glucose uptake before the induction of insulin resistance was confirmed." (PMID 39200235, 2024). "More widely used is the Homeostasis Model Assessment-Insulin Resistance (HOMA-IR) index, but it is also restricted by individuals receiving insulin therapy or those with non-functionality β individual cells." (PMID 39054513, 2024). "As expected, SKO mice failed to respond to insulin during an ITT, consistent with severe insulin resistance." (PMID 38745956, 2024). "Despite well-recognized changes in insulin resistance with pregnancy, there was no change in insulin receptor (CD220) expression which is perhaps unsurprising given monocytes are insulin independent." (PMID 38736550, 2024). "IGN has been reported as an important signal in the central enhancement of whole-body insulin sensitivity, and mice lacking intestinal G6PC, the key enzyme of IGN, develop insulin resistance despite a normal diet." (PMID 38542455, 2024). "Insulin failed to induce AKT activation in HFD males, suggesting the presence of insulin resistance in these animals." (PMID 39339665, 2024). "In contrast, in DDW medium, these agents had little effect on glucose uptake in the absence of insulin stimulation, and only a slight increase was observed with decreasing DDW concentrations before insulin resistance was induced." (PMID 39200235, 2024).
Insulin resistance (continued). "The most common factor in the delay of early initiation of insulin therapy is Psychological insulin resistance (PIR), a psychological state in which a patient experiences cognitive difficulties (negative perceptions) regarding aspects of insulin therapy." (PMID 39453515, 2024). "A total of 39 targets were positively correlated with FPG, but none of the tested targets were correlated with insulin, C-reactive protein (CRP) or Homeostatic Model Assessment of Insulin Resistance (HOMA-IR) levels." (PMID 39000149, 2024). "At the proteome level, the ephrin type-A receptor 2 (EphA2) showed an insulin-induced increase in expression, which occurred through the ERK signaling pathway and was concordantly independent of insulin resistance." (PMID 39572596, 2024). "Insulin-sensitive non-diabetics and prediabetic individuals did nothave higher CRP levels than individuals who were both insulin resistance and prediabetic.These variations were believed to be somewhat caused by variations in body weight." (PMID 39132231, 2024). "Psychological Insulin Resistance (PIR) and negative perceptions regarding insulin treatment are noteworthy challenges in T2DM management, which hinder the timely initiation of insulin treatment." (PMID 39453515, 2024). "In T1DM, insulin productionis very low or nonexistent, resulting in high blood glucose levels.In T2DM, insulin resistance leads the pancreas to produce more insulin,increasing its levels in the blood." (PMID 39371966, 2024). "We found a single study that evaluated insulin secretion by homeostatic model assessment of β-cell function (HOMA-β) and insulin resistance by HOMA-IR in nondiabetic middle-aged Japanese people." (PMID 39188637, 2024). "The subject’s average fasting glucose level was 93.68 mg/dL (SD = 11.57), the median fasting insulin level was 6.05 μIU/mL (1.1–23.6), and the median HOMA-IR was 1.41 (0.24–5.56), which indicated that the majority of subjects did not have insulin resistance." (PMID 38589425, 2024). "Various surrogate markers of insulin resistance have been developed, capable of predicting coronary artery disease (CAD) without the need to detect serum insulin." (PMID 38907271, 2024). "This study further confirms the previous findings, as no systemic insulin resistance in this study occurred, as evidenced by no changes in fasting blood glucose, AUC OGTT, serum insulin and HOMA-IR." (PMID 39598339, 2024). "Our current findings show that metformin improved glucose intolerance but did not alter insulin concentrations nor the HOMA-IR index, indirect markers of peripheral insulin resistance at 18 months of age in tau-VLW mice." (PMID 39170185, 2024). "In short, acute xylitol administration leads to small rises in glucose and insulin concentrations and chronic intake has no impact on blood glucose and insulin concentrations during an OGTT, or on insulin resistance (HOMA-IR)." (PMID 38474749, 2024). "The Insulin resistance (HOMA‐IR) index and insulin levels in blood samples of cases and controls were not measured, which is another limitation." (PMID 38468402, 2024). "Third, insulin resistance was based on HOMA-IR and not on euglycemic insulin clamp analysis, which is the gold standard method for the assessment of insulin sensitivity." (PMID 38902745, 2024). "As for the homeostasis model assessment-estimated insulin resistance (HOMA-IR) index, there is very little value in patients treated with insulin or those without functioning beta cells, although it’s currently widely used." (PMID 38822373, 2024).
Insulin resistance (continued). "Second, this study was powered for the primary outcome, i.e., changes in insulin sensitivity after HIIT training across all groups, but not for sub-analyses, e.g., according to insulin resistance or use of medication." (PMID 39626509, 2024). "In summary, fructose supplementation increased weight gain, impaired insulin tolerance at 120 min, and reduced hepatic insulin signaling on the BCD, while fructose intake on LXD did not induce weight gain and even improved some measures of insulin resistance." (PMID 39796558, 2024). "Although the dynamic homeostasis model assessment of insulin resistance (HOMA-IR) has gained popularity and recognition as a valid tool, it is not recommended for use in patients who are on insulin therapy." (PMID 38200157, 2024). "Unlike HEC and HOMA-IR, TyG-BMI does not require insulin but only FPG, TG, and BMI, and is a simple and effective indicator for the diagnosis of insulin resistance." (PMID 38783200, 2024). "DRD1 and DRD2 gene expression in subcutaneous adipose tissue correlated positively with clinical markers of insulin resistance (e.g. HOMA-IR, insulin, and triglycerides) and central obesity in subjects without T2D." (PMID 37752366, 2024). "Insulin resistance stands prominently as a pivotal factor in the pathogenesis of T2DM, driven not solely by the compromised transmission of the insulin signaling pathway but also entailing a myriad of intricate metabolic determinants." (PMID 39050247, 2024). "The levels indicating beta cell function (HOMA2-B), insulin sensitivity (HOMA2-S) and peripheral insulin resistance (HOMA2-IR) were not significantly different between the two groups (p = 0.832, p = 0.703 and p = 0.741, respectively)." (PMID 38842763, 2024). "Plasma substrates and hormones (glucose, insulin, and plasma lipids), markers of inflammation (C-reactive protein [CRP] and ferritin), and the homeostasis model assessment of insulin resistance (HOMA-IR) score did not change after orange supplementation." (PMID 39339791, 2024). "The insulin resistance typical of T2DM occurs also in bone tissue, where insulin does not exert its full anabolic effect." (PMID 38982537, 2024). "Yet, Larner’s study indicates clearly that we need not postulate insulin resistance to explain PCOS pathogenesis, given that insulin hypersensitivity is likely a common feature of PCOS ovaries." (PMID 37047265, 2023). "We assessed the effects of MOJ intake on the insulin resistance by comparing the fasting glucose, fasting insulin and HOMA-IR values in the volunteers with or without insulin resistance." (PMID 37469434, 2023). "Indeed, high-fat-diet-induced insulin resistance in rodents is associated with increased markers of mitophagy, while ablation of the key mitophagy regulating protein FUNDC1 within skeletal muscle does not impair mitochondrial bioenergetics or induce insulin resistance within this tissue." (PMID 37153211, 2023). "In line with the hypothesis that insulin resistance and longevity are not necessarily coupled, Irs1KO mutant males showed a similar life-span extension to females but showed improved insulin sensitivity, and nKO male mice showed improved insulin sensitivity but were not long-lived." (PMID 36812323, 2023). "We need not postulate insulin resistance to explain PCOS pathogenesis, given that insulin hypersensitivity is likely a shared feature of PCOS ovaries." (PMID 37047265, 2023). "In fact, the opposing action of insulin and leptin can explain why animals with HFHSD did not develop polyphagia despite the potential development of central insulin resistance." (PMID 37929025, 2023). "Furthermore, in bovine aortic ECs, insulin stimulated ET-1 production via the MAPK/ERK pathway; this, coupled with the inhibition of eNOS activation via the downregulation of the PI3K/Akt pathway in insulin resistance, may further enhance levels of ET-1 and result in pathology." (PMID 37511055, 2023).
Insulin resistance (continued). "For example, the insulin resistance state affects different tissues in the two conditions (peripheral in IGT vs. hepatic in IGF) and only IGT subjects show a defect in late-phase insulin secretion in a non-pregnant population." (PMID 37386647, 2023). "It is important to distinguish between reduced insulin sensitivity and IR as most women with PCOS have reduced insulin sensitivity, but not all women with PCOS meet the experimental criteria for insulin resistance." (PMID 37109585, 2023). "Measurements of ITT did not indicate enhanced insulin sensitivity in the Taz-KO mice, although the ITT is more broadly designed for detecting insulin resistance rather than sensitivity." (PMID 36831174, 2023). "In terms of insulin resistance and secretion, ginseng significantly reduced the Homeostatic Model Assessment of Insulin Resistance scores (GRADE level: low), but did not affect fasting insulin levels (GRADE level: very low)." (PMID 37465522, 2023). "Insulin resistance, a condition encountered in 85% of PCOS women regardless of their BMI, represents the need for higher-than-normal quantities of insulin to maintain normal blood glucose." (PMID 36676074, 2023). "Our analyses suggest that the inflammation is due to PCOS-related insulin resistance rather than PCOS itself; but further evidence is required to support the mechanisms of inflammation and the role of insulin in PCOS." (PMID 37355686, 2023). "However, very few peripheral insulin can access the brain through the BBB in T2D due to the hyperinsulinemia and brain insulin resistance, which was also proven in our animal experiments, as subcutaneous insulin injection failed to remarkably increase the insulin level in CSF." (PMID 37667187, 2023). "Currently, the homeostasis model assessment of insulin resistance (HOMA-IR) is widely used to assess IR, but this model has limitations for patients receiving insulin treatment or those with non-functioning beta cells." (PMID 37993902, 2023). "This study clearly indicated that, even in the absence of overt insulin resistance, the ovaries of PCOS women display an intrinsic sensitivity to normal endocrine signaling (insulin and LH), which is ultimately responsible for increased androgen release." (PMID 37047265, 2023). "Our previous cross-sectional study revealed that increased insulin levels due to decreased MCRI and enhanced endogenous insulin secretion completely compensate for moderate peripheral insulin resistance in healthy non-obese subjects." (PMID 37373776, 2023). "While insulin resistance is not emphasized in daily practice, HOMA-IR or other insulin measurements are more widely used." (PMID 35765946, 2023). "Multiple studies have shown that FGF21 can alleviate insulin resistance, but interestingly, the synergistic effect of FGF21 and insulin is not negligible." (PMID 38069273, 2023). "Another main finding, that there was no change in insulin resistance, suggests that any beneficial effects of MTM on HbA1c were not mediated by increased insulin sensitivity." (PMID 37253820, 2023). "Although the homeostasis model assessment estimated insulin resistance (HOMA-IR) index has been widely used, its use is limited when individuals are under insulin treatment or are without functioning beta cells." (PMID 37845738, 2023). "Conclusively, insulin resistance is not a general feature of PCOS, since the prevalence of insulin alterations involves barely around 60% of patients." (PMID 37047265, 2023). "Furthermore, it does not identify whether hepatic or peripheral insulin resistance predominates or whether the cutoff value globally employed (2.5) is appropriate for the population under study, also considering the pulsatile nature of insulin secretion." (PMID 37443718, 2023). "Higher levels of this adipokine in patients with SSc were not directly related to BMI, patients’ age, and insulin resistance indices (HOMA-IR, fasting insulin levels), which were comparable in the SSc and control groups." (PMID 37373131, 2023).
Insulin resistance (continued). "Hyperglycemia and homeostasis model assessment-estimated insulin resistance (HOMA-IR) were significantly induced (p ˂ 0.05) in mice after 2 weeks of HFD consumption, however, insulin levels were not altered significantly." (PMID 36982743, 2023). "Although serum fasting insulin and HOMA-IR, as signs of peripheral insulin resistance, did not decrease significantly, mitochondrial mass in skeletal muscle decreased." (PMID 37929025, 2023). "While there is much debate in the literature about the relationship between mitochondrial capacity and function and insulin action, the reduction in oxidative capacity induced by HDAC4 and 5 did not result in overt insulin resistance." (PMID 38040704, 2023). "In addition, we did not measure insulin levels or perform glucose tolerance testing, which might have provided insight into the possible development of insulin resistance following the consumption of a HFD, but it has been shown that FVB/N become more glucose intolerant after consuming a HFD." (PMID 37948457, 2023). "Insulin resistance is reduced after WL intervention; the ZAG and HSL expression did not significantly change, suggesting that the improvement of insulin sensitivity after WL is not regulated by HSL or ZAG." (PMID 37830580, 2023). "High-fructose corn syrup does not elevate insulin or leptin levels as glucose does, and thus stimulates hepatic de novo lipogenesis, contributing to NASH and insulin resistance." (PMID 37233716, 2023). "Fasting glucose, insulin, triglyceride, GLP-1, and calculated insulin resistance (HOMA-IR) did not change significantly within or between treatments." (PMID 37513677, 2023). "Such moderate positive correlations are maintained and increased only in patients with insulin resistance in relation to DRD1 (r = 0.386, p = 0.0008) and DRD4 (r = 0.419, p = 0.0003), being absent in insulin-sensitive patients." (PMID 36768789, 2023). "In addition to the adaptive increase of blood adiponectin level, insulin resistance or compromised insulin receptor signaling pathway may downregulate expression of insulin degrading enzyme (IDE), a downstream target of the pathway and protease that digests Aβ as well as insulin." (PMID 37191420, 2023). "Although oral administration of NR did not improve insulin sensitivity or affect GLP-1 secretion, oral intake of NMN alleviated insulin resistance in obese prediabetic females." (PMID 36986224, 2023). "Both tryptophan and kynurenine, but not serotonin, correlated with insulin resistance as assessed by HOMA-IR, insulin and c-peptide, and also when adjusting for age and pubertal stage." (PMID 35057467, 2022). "We found that low-dose TCDD-treated AhR-knockdown cells also showed suppressed insulin-induced glucose uptake and Ca2+ efflux, suggesting that the TCDD-mediated insulin resistance is also independent of AhR." (PMID 36358481, 2022). "Neither glucose nor insulin area-under-the-curve (AUC) during the OGTT, or the homeostatic model assessment of insulin resistance (HOMA-IR) changed in any group." (PMID 35761262, 2022). "The Korean National Health and Nutrition Examination Survey tested for nonlinear relationships between serum insulin and BMD by level of insulin resistance; its findings, though cross-sectional, parallel those observed here." (PMID 36278482, 2022). "Fasting participants with T2D had 103%, 160% and 76% higher concentrations of plasma glucose (p < 0.0001), insulin (p = 0.0002) and FFA (p = 0.015) respectively, and 425% higher insulin resistance (p = 0.0002) compared to non-diabetic controls." (PMID 35052658, 2022). "PEA, a non-canonic endocannabinoid, is recognized as an insulin sensitizer and AMPK activator, able to improve hepatic lipid and glucose homeostasis, steatosis, insulin resistance and serum leptin/adiponectin ratio." (PMID 35214069, 2022).